AR (androgen receptor)
Diseases named in the same sentence as AR in open-access papers (continued):
Sharing a sentence is not in itself a finding about the gene and the disease.
cancer (continued). "Below, we selected AR and ERR to exemplify how receptors of this type contribute to cancer cell metabolic reprogramming in response to redox fluctuation." (PMID 36551308, 2022). "Although several studies manifested that TFF1 was related to different kinds of carcinoma, few studies on TFF1 in AR-positive TNBC have been reported." (PMID 36157217, 2022). "By shifting S1P and S2P to ATF6 and simplifying the ER stress pathway, cancer cells can rapidly provide an appropriate level of UPR to compensate for the need for AR protein itself and subsequent AR-triggered proliferation." (PMID 34521429, 2021). "Its ligand, PDL1 predicted AR positivity, as AR-positive TNBC was threefold more likely to express PD-L1 on cancer cells." (PMID 33915941, 2021). "ESR1, TOR1AIP1, STAT1, COL1A1 were identified as high expression, while EGFR, AR, GATA2 were identified as a low expression in both cancer types." (PMID 33907495, 2021). "Among its related pathways are Transcriptional misregulation in cancer and Activated PKN1, which stimulates transcription of AR (androgen receptor) regulated genes KLK2 and KLK3." (PMID 33613644, 2021). "To explore the correlation between AR gene and GBM cancer stem cell genes in The Cancer Genome Atlas (TCGA) database, we selected 10 well-known GBM cancer stem cell genes." (PMID 34094902, 2021). "Although initially responding to androgen deprivation therapy (ADT), cancer cells can adapt to ADT and restore AR signalling under low levels of androgens, and consequently, the disease progresses to more aggressive castration-resistant prostate cancer (CRPC)." (PMID 34940756, 2021). "Androgen receptor (AR)-depleted CAF enhances the production of IFN-γ and M-CSF, leading to increased cancer stemness." (PMID 34760886, 2021). "PI3K/AKT and AR signaling is also known to interact with MAPK and can promote cancer survival via compensatory activation." (PMID 34439133, 2021). "Since cancers that exhibit high TRF2 levels have a poor prognosis and exhibit increased resistance to chemotherapy, AR and AD are therapeutic agents of interest for such tumors." (PMID 34203903, 2021). "AR has been a critical target for the treatment of PCa, and while ADT has been effective in preventing cancer cell proliferation, progression to a more aggressive phenotype is inevitable." (PMID 35372800, 2021). "Co-treatment with DIM and ENZ regulated Wnt signaling to reduce not only the AR expression, but also the AR-v7 expression, indicating suppression of EMT that inhibits cancer cell proliferation, invasion and migration to ameliorate ENZ resistance." (PMID 33441906, 2021). "Data confirmed a significant reduction of AR activity (p = 0.020) and a concomitant increase of C4-2B GFP+ cell proliferation when cancer cells grew in the presence of OBs." (PMID 34966687, 2021). "In DNPC, the mechanism of cancer progression is totally different from AR-dependent CRPC, therefore, different signaling from AR and AR-related signaling as a treatment target must be investigated hereafter." (PMID 33921329, 2021). "Subsequently, we selected an enriched pathway (hsa05200: pathways in cancer) and intersected with the top 10 hub genes, and we showed that there are 4 overlapping genes (AKT1, MAPK8, AR, and MDM2)." (PMID 33511213, 2021). "Further explorations revealed that AR downregulation by BM-MSCs increased the stemness of PCa, owing to the upregulation of several CSC (cancer stem cells) related markers such as CXCR4, ZEB1, and Snail1." (PMID 34692685, 2021). "Several cancer-relevant proteins have been identified as the substrates of SPOP, such as androgen receptor (AR), SRC-3, TRIM24, and BRD4, and these proteins are aberrantly upregulated in SPOP-mutated PCa cells and patient tissues." (PMID 34599168, 2021). "Second, we found that a KLF5 super-enhancer active in other cancers displayed a high density of active chromatin marks in PC-3 cells and that KLF5 expression in PC-3 cells was insensitive to AR re-expression." (PMID 34737261, 2021).
cancer (continued). "In some cancer types, VEGF, AR, and HIF-1 cross talk have already been recognized, similar to AR/MMP9/VEGF cross-talk." (PMID 33920263, 2021). "Our results provide support for the development of clinical trials evaluating combined p110α (BYL719) and AR inhibition in patients with mCRPC harboring PIK3CA-mutant, PTEN wild-type cancers." (PMID 34417459, 2021). "Here, we show that SPOP- and ERG-mutant cancer subtypes are driven by antagonistic tumorigenic pathways involving fundamentally different roles of SPOP and androgen receptor signaling levels." (PMID 33531470, 2021). "The impact of the molecular interplay between the AR and DPP4 is of utmost importance to clarify and further understand the impact of these commonly used diabetic drugs on the most frequent cancer in males." (PMID 34055551, 2021). "In 5,414 cancers with available AR expression data, the intensity of PNUTS staining was highly related to AR levels." (PMID 32377272, 2020). "The AR expression of SHL (100 μg/mL, 0.66-fold; 200 μg/mL, 0.54-fold) was similar to that of enzalutamide (0.69-fold), which is an anti-cancer agent and AR inhibitor." (PMID 32972001, 2020). "The IHC panel included markers for cancer activated fibroblasts (CAFs), blood vessels and steroid hormone receptors ((SHR): androgen receptor (AR), progesterone receptor (PR) and estrogen receptor (ER))." (PMID 33370412, 2020). "In hormone-sensitive PCa, AR signaling is regulated by lncRNAs, such as HOTAIR, which represses the degradation of the E3-ubiquintin - AR complex, which induces castration resistant prostate cancer (CRPC) to promote metastasis of cancer cells." (PMID 32164712, 2020). "Cancer signaling pathways (hsa05200) showed that HSP90B1 promotes cell proliferation and evades apoptosis by activating of androgen receptor (AR) and PSA." (PMID 32537125, 2020). "Considering the fact that AR and ESR1 play a role in cell proliferation and angiogenesis in cancer, it is likely they exert similar functions in placentas." (PMID 33029224, 2020). "In our search for novel androgen receptor antagonists, we focus on the Traditional Chinese Medicine (TCM), which has been used for thousands of years to prove effective in the treatment of cancer." (PMID 33094102, 2020). "Here, we used LNCaP and 22Rv1 cancer cells expressing endogenous AR and PSA to examine the relationship between AR and SIRT7 and the effects of the latter on AR signaling-mediated cancer proliferation and aggressiveness." (PMID 32019578, 2020). "In this cohort, Sox2 and AR had independent and opposite effects on DMFI, DFI and cancer-specific survival, which triggered the analysis of FMC subgroups according to Sox2 and AR expression." (PMID 33553286, 2020). "As in cancer cells, KDM1A binds to AR and ESR1 in trophoblast cells, and therefore is thought to play a role in regulating AR and ESR1 signaling in the placenta." (PMID 33029224, 2020). "Information about the biological activity of SEMGs in cancer is also limited and only describes SEMG1 as a co-activator of androgen receptor in prostate cancer." (PMID 33311447, 2020). "This study centred around two genes; NAALADL2 and TBL1XR1, both of which are attractive therapeutic targets with TBL1XR1 previously suggested as a potential cancer target; operating via the TGF-β signalling pathway and potentially regulating AR signalling." (PMID 32796921, 2020). "The TNM classification (T1–T4, N0–N3, and M0–M1), cancer grade (Grades I–III), and AR/PR/ER/HER2 expression level data that were related to the microarray were provided by the manufacturer." (PMID 32237061, 2020). "Many PCa relevant genes (e.g., AR, CD4423, MEAF624, and others) displayed isoform switch during cancer development and progression." (PMID 32350277, 2020).
cancer (continued). "Immunohistochemical (IHC) research of androgen receptor has been done only in cases with diagnosis of SDC, adenocarcinoma NOS, and carcinoma ex pleomorphic adenoma." (PMID 33327563, 2020). "It has been reported that miR-124 inhibits proliferation in cancer cells through targeting CDK4, CBL, Slug and androgen receptor." (PMID 31367191, 2019). "SFN has been shown to interfere with a key androgen receptor (AR) chaperone, Hsp90, by inhibition of histone deacetylase (HDAC) enzymes, which remove acetyl groups from histones, inhibiting HDAC activity within cancer cell lines." (PMID 31540470, 2019). "miR-205 actively targets the 3'UTR of some key genes such as AR, BCL2, ERBB3, PTEN, and VEGF-A that play important roles in cancer cell invasion and metastasis." (PMID 31756185, 2019). "The androgen receptor (AR) is expressed in TNBC, although its function in these cancers is still debated." (PMID 30872694, 2019). "Direct co-culture of androgen receptor-dependent/independent cell lines (LNCaP, C4-2B, and PC3) led cancer cells to display functional and molecular features as observed in vivo." (PMID 31044095, 2019). "Our study strongly supports the druggability of NRs in TME, notably AR and RARβ, which can mediate a CAF-directed cancer therapy." (PMID 30925918, 2019). "It has also been reported to promote PrCa growth by binding to SRC3, an androgen receptor co-activator and inducing increased expression of IGF1R, resulting in activation of the AKT signaling pathway and cancer cell growth." (PMID 30958860, 2019). "A study had identified a crosstalk between AR and epidermal growth factor receptor (EGFR), which is involved in cancer cell growth, in ER-positive BC cells." (PMID 31151151, 2019). "To estimate the impact of AR on ROCK1 expression, we used AR expression data from a previous study, Data on both ROCK1 and AR were available from 6994 cancers." (PMID 31557128, 2019). "In this sense, the PI3K/AKT signaling pathway is a frequently dysregulated pathway in cancer, and specifically in PCa, wherein signaling cross-talk and functional synergism between PI3K/AKT and AR pathways have been previously reported." (PMID 31500112, 2019). "Initially, on the basis of several previous studies, we focused on six different STR loci, including AR, BAT-25, D5S346, ER1, ER2, and FGA, which were reported to be closely related to the occurrence of malignant carcinomas." (PMID 31179189, 2019). "Particularly in AR+ carcinomas, ARNILA is suppressed by the action of DHT and AR, resulting in the decreased adsorption of miR-204 thus favoring Sox4 expression inhibition." (PMID 30941159, 2019). "In previous studies, STR loci AR, BAT-25, D5S346, ER1, ER2, and FGA were reported to be closely related to the occurrence of malignant carcinomas." (PMID 31179189, 2019). "A high level of “luminal-like” genes such as AR and GATA3 in LAR-TNBC subtype has a relatively favorable prognosis compared to tumors expressing cancer stem cell markers." (PMID 30034618, 2018). "Although a minimum level of AR activity is required for baseline SRARP expression in AR+ cancer cells, higher levels of AR activity lead to another layer of SRARP regulation through AR‐mediated suppression of this gene." (PMID 29577611, 2018). "Our results suggest that upon ligand stimulation, AR increases EGFR expression, which in turn acts on AKT pathways to promote cancer cell survival and invasiveness." (PMID 30134822, 2018). "PCa patients initially respond positively to ADT, though most experience a relapse of the cancer to a hormone-refractory form called CRPC, which occur when cancer cells adapt to growth under low androgen conditions by constitutively upregulating AR." (PMID 29967592, 2018). "Despite several reports stating that AR expression is acquired in HER2/ESR1/PGR triple-negative cancers, here we show that a low percentage of these cancers express AR (~20%)." (PMID 30279965, 2018).
cancer (continued). "Since RORα and RORγ are dysregulated in multiple cancer types based on published articles, they likely participate in carcinogenesis through modulating molecules such as IL-17, PRMT2, and AR or as receptors for sterols, such as vitamin D3 derivatives." (PMID 29904382, 2018). "To provide cellular level evidence of AR‐Qs and AhR interactions, we introduced AhR knockdown in AR‐Qs transfected HEC‐1A cells and measured HEC‐1A cancer cell growth with colony‐formation assay." (PMID 28782227, 2018). "We found that the expression of AR and CK18 were elevated in cancer cells as compared to benign luminal cells or basal cells, which has been also reported earlier." (PMID 29138507, 2017). "Given the relationship between reduced stromal AR and cancer related progression and death, it may be more important to investigate either anti-androgen which affect only epithelial cells, or developing drugs which will decrease epithelial AR but enrich stromal AR signalling." (PMID 28117763, 2017). "Additionally there are a host of other chemokines produced by CAFs which may similarly be regulated any androgen, and could provide an avenue by which disruption of AR signaling in fibroblasts may change the migrationary potential of cancer cells thus affecting patient outcomes." (PMID 28117763, 2017). "Fibroblasts AR has the ability to regulate the ECM, which when lost will create an environment favourable for cancer cell invasion and metastasis." (PMID 28117763, 2017). "We highlight that the role of AR signaling and its interaction with WNT signaling in these two hormone-related cancer types are highly context-dependent." (PMID 28134791, 2017). "This study suggested that NKX3-1 forms a positive autoregulatory loop with AR and FOXA1, and mediates cancer cell survival via induction of RAB3B, a member of the RAS oncogene family." (PMID 28264478, 2017). "NR4A2 is a family member of AR (NR3C4), which is known to be activated downstream of the MAPK pathway in cancer and directly interacts with NFκB (specifically the REL subunit), as correctly predicted for NR4A2." (PMID 27078000, 2016). "Consistent with previous findings, we also found AR mRNA and protein levels were significantly reduced in the shDJ-1 knockdown MCF-7 cancer cells." (PMID 27582551, 2016). "It is well accepted that the androgen receptor (AR) is a major driver of CRPC, rendering the AR a potential anti-cancer target." (PMID 27598125, 2016). "Increased references in PubMed also provided us other hub proteins involved in cancer pathways, such as ESR1, PTEN, BCL2, AR and MAPK3." (PMID 27917343, 2016). "With multiple players involved in TNBC, the action of the AR in TNBC appears to be influenced by cross-talk with other pathways that differ between cell types and cancer subtypes." (PMID 27918430, 2016). "The results showed successful capture of the cancer cells using CD90 and AR staining methods in the blood mixture, and the detection rate was > 90%." (PMID 27340775, 2016). "While recombination with UGM can instruct NHPrE1/EV cells to form benign prostate glandular structures, constitutive expression of AR in NHPrE1 cells alters their response to gland-organizing signals from UGM, resulting in the development of carcinomas." (PMID 27611945, 2016). "Activation of the AR regulator HIPK2 (Homeodomain-Interacting Protein Kinase 2) by genotoxic stress triggers apoptosis in part through phosphorylation of CtBP1, which causes CtBP1 degradation; loss of this signaling could plausibly cause predisposition to multiple forms of cancer." (PMID 26485759, 2015).
cancer (continued). "Here we assessed stromal and epithelial AR levels in paired BPH and cancer samples from the same patients, allowing discrimination of changes specific to cancer stroma from those related to an individual patient or prostate." (PMID 25965833, 2015). "We have previously reported that the AR promotes glycolysis and anabolic metabolism; many of these metabolic pathways are also MYC-regulated in other cancers." (PMID 25869206, 2015). "Consistently, AR and UPR gene expression were correlated in human PCa, and spliced XBP-1 expression was significantly upregulated in cancer compared with normal prostate." (PMID 25864123, 2015). "In hormone dependent cancer cells ATAD2 is an estrogen and androgen responsive gene and also a co-activator for full activity of ER and AR." (PMID 26308378, 2015). "While parental LNCaP cells exhibited severe growth inhibition in response to AR siRNA, simultaneous knockdown of PMEPA1 rescued the growth of cancer cells." (PMID 25883222, 2015). "Potential molecular proliferative signaling targets for anti-cancer activity of silibinin include the receptor tyrosine kinase, STAT, androgen receptor and NF-κB pathways, however, anti-cancer activity of SM is beyond the scope of the present review." (PMID 26785346, 2015). "The high number of cancers included in this analysis further enabled us to study the combined impact of the interrelated biomarkers HOXB13, AR, and PSA." (PMID 25825985, 2015). "Among them, a number of pathways have role reported in metastasis of cancers, such as TGFβ receptor, EGFR1, androgen receptor, Notch signaling pathways and few more." (PMID 25984907, 2015). "The survival of cancer foci, detected as p63−/CK8.18+, was similar in grafts from the four patients with PShTert-AR (65%, 11/17) and PShTert-ctrl (56%, 13/23) lines." (PMID 25965833, 2015). "Although, overexpression and a functional significance of CIP2A in androgen-independent cancer SCs implied AR-independent effects of CIP2A, we also have strong evidence for AR-mediated CIP2A regulation in AR-responsive cells." (PMID 25965834, 2015). "While re-activation of AR signaling and mitosis of cancer cells are two major features of CRPC, our study identifies catalytic Topo II inhibitors as a potential co-targeting approach in combination with AR pathway inhibitors in CRPC." (PMID 26009876, 2015). "Many AR targets affected by IGSF8 knockdown are known positive and negative regulators of cancer cell proliferation and survival." (PMID 26036626, 2015). "In this trial, researchers used an NGS platform similar to the one used in our study (AmpliSeq for cancer panel), but used Cytoscan for CNV analysis and an IHC panel including estrogen receptor (ER), progesterone receptor (PR), and androgen receptor (AR)." (PMID 26396172, 2015). "After verifying the biological meaning of the low-cost paths, the signal TGFβ1- TGFβR1- SMAD2/3- SMAD4- AR-OCIAD2 was discovered and explained TGFβ's stimulation on OCIAD2 expression in cancer." (PMID 24949437, 2014). "AR pathway is a driving force in CRPC, as seen from its deregulation in vast majority of these cancers." (PMID 25277175, 2014). "In human prostate tumor tissues, elevated cancer stem-like cell markers coincide with those cells exhibiting high STAT3 activity and low AR expression." (PMID 24722453, 2014). "Thus, AR/Src complex regulates multiple processes in EGF-stimulated HT1080 cells and led us to conclude that prevention of AR/Src Association, independent of the presence of androgens, impairs several properties that are crucial for cancer progression and invasiveness." (PMID 24130806, 2013).